CST3 (cystatin C)
Diseases named in the same sentence as CST3 in open-access papers (continued):
Sharing a sentence is not in itself a finding about the gene and the disease.
cardiovascular disease (continued). "Although the mechanism linking cystatin C with cardiovascular disease was currently not well known, numerous studies tried to explain it." (PMID 23843968, 2013). "In this study we measured the effect of bed rest on plasma concentrations of cystatin C, which is an emerging marker of cardiovascular disease." (PMID 22152087, 2011). "Consistent with previous analyses in older persons without CKD, cystatin C is a superior prognostic biomarker for the risk of death, cardiovascular disease, and CKD compared to serum creatinine and eGFR." (PMID 40983592, 2025). "Epidemiological studies show that high circulating cystatin C is associated with risk of cardiovascular disease (CVD), independent of creatinine-based renal function measurements." (PMID 37817071, 2023). "Elevated serum cystatin C levels were associated with coronary atherosclerotic plaque burden independent of traditional cardiovascular disease predictors as assessed by computed tomography coronary angiography." (PMID 37817071, 2023). "Our results demonstrated that serum cystatin C was strongly associated with severe plaque burden independent of traditional cardiovascular disease predictors." (PMID 37817071, 2023). "Cystatin C is also a stronger predictor of cardiovascular diseases compared to creatinine." (PMID 35862349, 2022). "We examined the associations between five markers of unhealthy ageing; Growth Differentiation Factor-15 (GDF-15), N-terminal pro-brain natriuretic peptide (NT-proBNP), glycated hemoglobin A1c (HbA1C), C-Reactive Protein (CRP) and cystatin-C; with risks of cancer and cardiovascular disease (CVD)." (PMID 34935094, 2022). "Epidemiological studies have shown that high circulating cystatin C is associated with a risk of cardiovascular disease (CVD) independent of creatinine-based renal function measurements." (PMID 31130557, 2020). "Creatinine is dependent on muscle mass, sex, and age, while cystatin C has been suggested to increase with inflammation and other extra-renal factors such as smoking, thyroid dysfunction, glucocorticoid use, and perhaps cardiovascular diseases." (PMID 30646571, 2019). "Cystatin-C is a marker of kidney function and also predicts cardiovascular disease." (PMID 31466396, 2019). "The underlying mechanisms by which cystatin C affects cardiovascular disease (CVD) are not very clear." (PMID 31317040, 2019). "These all demonstrated the prognostic significance of cystatin C in cardiovascular disease." (PMID 29254149, 2017). "Increased serum cystatin C levels are related to the prognosis of cardiovascular diseases." (PMID 29254149, 2017). "Cystatin C (Cyst C) is a novel biomarker of both latent renal damage and cardiovascular disease." (PMID 27843647, 2016). "Cystatin C is emerging as a new biomarker in cardiovascular disease." (PMID 24672725, 2014). "Markers such as fibrinogen, vitamin D, and cystatin C have a strong association with cardiovascular disease but as of yet have not been implemented in the clinic." (PMID 23630624, 2013). "In addition, no therapy has been evaluated to date that aimed to treat patients for cardiovascular disease on stratification by cystatin C values." (PMID 23630624, 2013). "Among these were protein biomarkers for different organ diseases such as deficiency of thyroid binding (thyroxine-binding globulin), chronic kidney dysfunctions (cystatin C), hypercoagulation disorders (plasminogen), and cardiovascular diseases (apolipoprotein A1, B)." (PMID 22538116, 2012). "Furthermore, cystatin C has been shown to be a better predictor of cardiovascular disease and mortality than creatinine, suggesting that it may have broader clinical utility beyond renal function assessment." (PMID 37509111, 2023).
cardiovascular disease (continued). "Another explanation for the association between cystatin C and PH is that cystatin C is also associated with oxidative stress and inflammation in the pulmonary vasculature, and its effect on cardiovascular disease outcomes has been shown to be independent of estimated GFR." (PMID 37633906, 2023). "The discordance of plasma Cystatin C levels with other renal function parameters such as plasma creatinine and urea could be influenced by multiple factors other than kidney function, such as cardiovascular disease and C-reactive protein levels." (PMID 35085251, 2022). "However, after adjusting for traditional cardiovascular risk factors and hs-CRP, an independent association between cystatin C and cardiovascular disease has been observed in most but not all studies." (PMID 34588554, 2021). "Besides age, gender, and BMI we found a distinct profile of markers for cardiovascular risk including NTproBNP, cystatin C, and AST associated with sCOMP values, indicating the need for more detailed investigation in correlation with the clinical manifestation of cardiovascular disease." (PMID 31963737, 2020). "Although serum cystatin C level has been reported to be a better predictor of cardiovascular disease and mortality than serum creatinine level, the latter may reflect GFR trends more directly, which may be useful for proper management of renal replacement therapy." (PMID 31185945, 2019). "The mechanisms of association between cystatin C and cardiovascular disease are not fully characterized, and several complementary hypotheses can be envisioned." (PMID 21977320, 2011). "Further, we used cystatin C as a marker of kidney function but can not rule out that it may also reflect cardiovascular disease risk above and beyond its relation to kidney function." (PMID 17903292, 2007). "GrimAge is based on seven plasma protein levels related to various diseases and conditions, including cardiovascular disease (Plasma B2M) and cognitive functions (Plasma B2M, ADM, Cystatin C, and leptin)." (PMID 40699219, 2025). "The serum creatinine–cystatin C ratio (SCR/CysC) and relative fat mass (RFM) are both important indicators reflecting muscle and fat content, respectively, and are closely related to metabolic diseases and cardiovascular diseases." (PMID 41497479, 2025). "In this model, NF-L was independently associated with cystatin C, BMI, age, self-reported neurological troubles and MMSE but not with history of fracture or cardiovascular disease." (PMID 35018623, 2022). "Levels of GDF-15, CRP and Cystatin C were determined in three repeated measurements collected 5 years apart in the DAN-MONICA (Danish-Multinational MONitoring of trends and determinants in Cardiovascular disease) cohort (participants at baseline n = 3785)." (PMID 29771963, 2018). "Taken together, these results indicate that cystatin C is not simply a marker of impaired kidney function but also a marker of cardiovascular disease." (PMID 28922364, 2017). "Cystatin C, an established sensitive marker of glomerular filtration, has also been widely recognized as a strong predictor of cardiovascular disease (CVD), this even in populations within apparently normal ranges of renal function." (PMID 27218257, 2016).
cancer (107 papers, 2004 to 2026). A tumor composed of atypical neoplastic, often pleomorphic cells that invade other tissues. "Clinically, elevated cystatin C levels in body fluids are associated with poor prognosis in cancer patients." (PMID 41233352, 2025). "High CST3 expression was also significantly associated with poor disease-free survival across all cancer patients, further implicating cystatin C in adverse clinical outcomes." (PMID 41233352, 2025). "Deletion of the CST3 gene, which encodes cystatin C, in host mice and tumor cells impaired tumor growth, whereas its overexpression accelerated cancer progression in LILRB2 and LILRB5 transgenic mice." (PMID 41233352, 2025). "Of the 29 enriched proteins, only two are described as inhibiting cancer cell growth and migration, as well as causing lysosomal/mitochondrial dysfunction and increasing apoptosis: cystatin C (through its inhibition of cathepsins) and decorin." (PMID 41300368, 2025). "Epidemiological studies and large-scale data analyses have linked elevated cystatin C expression to increased all-cause and cancer-specific mortality across diverse populations." (PMID 41233352, 2025). "When we looked at each individual GI cancer, cystatin C remained significantly associated with the cancers with an adjusted odds ratio of at least 1.97." (PMID 38263244, 2024). "In cancer, CST3 has also been linked to the removal of T cells and a lack of response to blocking immune checkpoints." (PMID 36969056, 2023). "In a large-scale longitudinal analysis of middle-aged and elderly individuals, this study found that elevated concentrations of cystatin C are associated with an increased risk of all-cause, cardiovascular and cancer mortality." (PMID 36564420, 2022). "Our study indicates that an elevated plasma cystatin C concentration is associated with an increased risk of all-cause, cardiovascular and cancer mortality both men and women among the middle-aged and elderly individuals." (PMID 36564420, 2022). "Rates of all-cause, cardiovascular and cancer mortality increased in association with increases in cystatin C concentrations assessed as quartiles." (PMID 36564420, 2022). "This study allowed us to have an umbrella view of the associations between five biomarkers linked to biological ageing (GDF-15, NT-proBNP, HbA1C, CRP, cystatin-C) and cancer and CVD risks." (PMID 34935094, 2022). "We are not aware of other studies, so far, that prospectively examined the association of cystatin-C in initially cancer free subjects with later cancer risk." (PMID 34935094, 2022). "It was the first study to assess the associations between combinations of biomarkers linked to biological ageing (GDF-15, NT-proBNP, HbA1C, CRP, cystatin-C) and cancer risk." (PMID 34935094, 2022). "With regard to cancer mortality, there is very limited evidence examining the association of cystatin C with cancer mortality." (PMID 36564420, 2022). "In conclusion, this study indicates that an elevated plasma cystatin C concentration is associated with the risk of all-cause, cardiovascular and cancer mortality both men and women among the middle-aged and elderly individuals." (PMID 36564420, 2022). "Our study indicated that a higher cystatin C concentration is associated with an increased risk of cancer mortality." (PMID 36564420, 2022). "Cathepsins have been implicated as biomarkers for cancer progression and metastasis; being a protease, it has an inherent tendency to interact with Cystatin C, a cysteine protease inhibitor." (PMID 35053201, 2021). "Although these confounders are unlikely to have major impact on our results, they need to be acknowledged when interpreting Cystatin C values properly, especially considering that some types of neuromuscular diseases are known to increase cancer risk." (PMID 34630276, 2021). "Our study found CST3 down-regulated in CRC stages, whereas a number of studies have associated up-regulation of CST3 associated with progression of cancer." (PMID 31467500, 2019).
cancer (continued). "In this study, we showed that interpersonal variability in macrophage-assisted cancer cell invasion is associated with patient variability in macrophage cathepsin activity and cystatin C level." (PMID 26349896, 2015). "We showed that there is patient-to-patient variability in macrophage cathepsin activity and secreted cystatin C level and that variability is associated with interpersonal variability in macrophage-mediated cancer cell invasion." (PMID 26349896, 2015). "More than 10 years have passed since the generation of the first cystatin C–deficient mouse to test its function in cancers." (PMID 21085595, 2010). "The multivariable-adjusted HRs (Model 2) of all-cause, cardiovascular and cancer mortality with the lowest quartile (Q1) of cystatin C concentrations as the reference were 1.92 (1.62–2.28), 1.98 (1.48–2.65), and 1.62 (1.13–2.32), respectively, for the highest quartile (Q4) (all P for trends < 0.05)." (PMID 36564420, 2022). "Overall, monitoring cystatin C concentration may help identify individuals who are at higher risk of all-cause, cardiovascular and cancer mortality." (PMID 36564420, 2022). "This discrepancy could be due to the dissimilar biological features between diverse tumor types, and the probability that the role of cystatin C might vary according to type of cancer, cause, and site in addition to stage of cancer." (PMID 28282874, 2017). "Previously the level of cystatin C has been associated with cardiovascular and as well as cancer mortality in healthy subjects, which however, could not be sustained in the present multivariable analyses." (PMID 24312445, 2013). "Additionally, evaluating the risks of all-cause, cardiovascular, and cancer mortality associated with each 1 mg/L increase in cystatin C concentrations revealed multivariable-adjusted HRs (95% CIs) of 1.51 (1.44–1.58), 1.49 (1.39–1.61), and 1.24 (1.05–1.47), respectively." (PMID 36564420, 2022). "In addition to its role in physiological processes by controlling extracellular proteolysis via inhibition of cysteine proteases, cystatin C has been associated with different pathological conditions, such as neurodegenerative disorders, inflammatory and cardiovascular diseases, and cancer." (PMID 29088746, 2017). "Given these divergent roles, understanding the precise function of cystatin C in cancer biology has become an important area of investigation." (PMID 41233352, 2025). "Our study is likely to be the largest routine care cohort worldwide with information on mGFR, creatinine, and cystatin C using state-of-the-art measures, and with cancer registry linkage, to facilitate this type of analysis." (PMID 40973716, 2025). "In recent years, the involvement of cystatin C in the antitumor immune responses and an elevated expression of Cys C in cancer tissues have been reported, above all in urogenital malignancy, and seem to be correlated with prolonged time of chemotherapy." (PMID 39861464, 2025). "The implications of using more accurate estimates of GFR, such as eGFRcr-cys, for cancer treatment safety and clinical outcomes would benefit from prospective confirmation, which would require routine testing of cystatin C in clinical cancer trials." (PMID 40973716, 2025). "Our patient cohort also exhibited increased mean cystatin C values prior chemotherapy, with nearly 75% of cancer patients having cystatin C values above the upper reference range boundary." (PMID 41010375, 2025). "Another large‐scale study involving 3060 cancer patients reported that the creatinine‐to‐cystatin C ratio at diagnosis significantly predicted both 6‐month and 1‐year mortality." (PMID 41216846, 2025). "Bioinformatic analysis of data from The Cancer Genome Atlas (TCGA) revealed a modest correlation between high CST3 expression and poor overall survival across all cancer patients (P > 0.05, but with a trend toward significance)." (PMID 41233352, 2025).
cancer (continued). "To investigate the potential role of cystatin C in cancer development, we measured circulating serum concentrations of cystatin C in healthy donors and cancer patients." (PMID 41233352, 2025). "Nevertheless, targeting cystatin C represents a scientifically sound and potentially transformative direction for treating cancer and amyloid disorders." (PMID 41233352, 2025). "Among the cancer patients surveyed, the majority presented elevated serum cystatin C levels compared with those of healthy controls." (PMID 41233352, 2025). "Although the evidence for cystatin C as a biomarker for kidney function in cancer patients is ambiguous, our study showed good predictive performance of the CKD-EPICR-CYS equation." (PMID 39365467, 2024). "Myosteatosis is a well-established predictor of poor prognosis in many types of cancer, and a decreased Creatinine/Cystatin C ratio (CCR) is a known indicator of unfavorable outcomes in patients with metabolic disorders and cancer." (PMID 38706605, 2024). "At present, the relationship between the creatinine/cystatin C ratio and the prognosis of patients with cancer has attracted more and more attention." (PMID 37409249, 2023). "Some markers CD14 (monocyte), CD3D (CD4+T cells), CD3E (CD8+T cells), CD68 (macrophage), CST3 (myeloid cells), GNLY (NK cells), KRT18 (epithelial cells), and NKG7 (NK cells) were positively associated with TMSB10 in all cancers." (PMID 37275863, 2023). "In a cohort of 1869 patients with cancer with simultaneous SCr and cystatin C measurement as a part of clinical care, discordancies between eGFRcr and eGFRcys were common." (PMID 37405775, 2023). "Considering that cystatin C is expressed in all nucleated cells, and patients with cancer have high cell turnover, the correlation of cystatin C with LDH is of special interest." (PMID 36143104, 2022). "The use of the equation with cystatin C alone or in combination with creatinine should always be performed considering high cell turnover in cancer patients." (PMID 36143104, 2022). "Meanwhile, although not statistically significant, when assessing OS at 100 months, the authors still found that patients with low cystatin C expression in cancer tissue had a poorer prognosis than those with high levels (p = 0.307)." (PMID 36589819, 2022). "The level of cystatin C correlated with the level of LDH, suggesting that the use of cystatin C-based calculations of GFR in cancer patients with elevated LDH should be used with caution." (PMID 36143104, 2022). "Nonetheless, evidence regarding the relationship between cystatin C concentration and cancer mortality is very limited." (PMID 36564420, 2022). "The differences were statistically significant (P < 0.001), suggesting that cystatin C protein expression levels were generally downregulated in cancer tissues compared with the benign fraction of pathological specimens." (PMID 36589819, 2022). "The cysteine protease inhibitor cystatin C is synthesized in all nucleated cells, including cancer cells." (PMID 36143104, 2022). "The cut-off values of serum cystatin C in three papers were all in the range of around 1.1 mg/l, which was broadly consistent with the levels of patients with other cancer types." (PMID 36589819, 2022). "Here, we studied the effects of external addition of the most abundant human cystatin, cystatin C, on viability and proliferation of cancer cells in culture." (PMID 33837649, 2021). "Meanwhile, the 2012 CKD-EPI creatinine-cystatin C equation was the least precise and the least accurate eGFR equation in cancer patients as determined by the standard deviation of the absolute difference and root-mean square error (RMSE), respectively." (PMID 31852941, 2019). "Other candidates, such as PRRX2 and CST3, confer metastatic properties to cancer cells through the TGF-β pathway." (PMID 30102725, 2018).